ORAI1 (ORAI calcium release-activated calcium modulator 1)
Diseases named in the same sentence as ORAI1 in open-access papers (continued):
Sharing a sentence is not in itself a finding about the gene and the disease.
breast cancer (continued). "In contrast to STIM1 and Orai1, Orai3 has no N-glycosylation consensus motifs; therefore, we have focused our studies in the functional role of STIM1 and Orai1 glycosylation in SOCE in the breast cancer cell types as compared to MCF10A breast epithelial cells." (PMID 36612199, 2022). "SK3/Orai1 co-regulation is responsible for breast cancer cell proliferation and migration or can even trigger bone metastasis." (PMID 35327543, 2022). "By contrast, breast cancer cells scape from this regulatory mechanism, so that, SOCE is independent on STIM1 or Orai1 N-linked glycosylation." (PMID 36612199, 2022). "The aim of this study was to analyze Orai1 and STIM1 N-linked glycosylation in SOCE in breast cancer cells and to ascertain the potential functional relevance of this post-translational modification in the development of cancer hallmarks." (PMID 36612199, 2022). "Studies have assessed the consequences of inhibiting or silencing ORAI1 in breast cancer cells and suggested a role for ORAI1 in the proliferation and invasion of these cells." (PMID 35682546, 2022). "Because the interplay between SK3 and Orai1 that triggers breast cancer cell migration occurs in cholesterol-rich regions, we present here recent findings on the individual regulation of SK channels by lipids, specifically, PIP2 and cholesterol." (PMID 36612099, 2022). "SICE includes the activation of ORAI1 by the secretory pathway Ca2+-ATPase 2 pump (SPCA2), which is implicated in the promotion of tumorigenesis in breast cancer." (PMID 35682546, 2022). "As elevated ORAI1 expression is a feature of basal breast cancer cells, we used basal A MDA-MB-468 and basal B MDA-MB-231 breast cancer cells in these studies, which are two of the most widely used basal breast cancer cell lines." (PMID 35682546, 2022). "Using a CRISPR-Cas9 and a rescue approach, this study investigated the role of ORAI1 on gene transcription in basal breast cancer cells." (PMID 35682546, 2022). "The consequence is that AC8 enhances Orai1-mediated SOCE in breast cancer cells attenuating Orai1α CDI." (PMID 36498894, 2022). "These assays revealed that NCL overexpression promoted proliferation and growth of breast cancer cells, but treatment with Orai1 channel blocker 2-APB abolished the promoting effects of NCL on cell proliferation and clonogenicity." (PMID 36109490, 2022). "For example, SK3 and Orai1 colocalized in cholesterol-rich regions in breast cancer cells, the disruption of which abolished SK3-Orai1 interplay, cancer cell migration, and bone metastasis." (PMID 36612099, 2022). "Blocking the Orai1 channel or NCL-Orai1 interaction inhibits the promoting effects of NCL on breast cancer cells proliferation." (PMID 36109490, 2022). "Several studies show an alteration of ORAI1-mediated Ca2+ influx and/or a remodeling of the ORAI1 expression in breast cancers." (PMID 35682546, 2022). "MTT assay revealed that Orai1 peptides treatment reversed the increased cell proliferation of breast cancer cells induced by NCL overexpression." (PMID 36109490, 2022). "Blocking the NCL-Orai1 interaction by synthesized Orai1 peptide can effectively reduce the intracellular calcium influx and suppress the proliferation of breast cancer cells in vitro and in vivo." (PMID 36109490, 2022). "It has already been established that the Orai1 channel is involved in the migration of human breast cancer cells." (PMID 34943998, 2021). "The hEag1 K+ channels are essential for breast cancer cell migration because they promote Orai1-mediated Ca2+ current." (PMID 36046433, 2021). "Concerning CRAC channels, Orai1 has been reported to be overexpressed in all the breast cancer cell subtypes investigated, and breast cancer cell biology is strongly dependent on this channel." (PMID 35008277, 2021). "In Summary, our results reveal the great heterogeneity in Orai1 and Orai2 channel expression between different breast cancer cell lines." (PMID 35008277, 2021).
breast cancer (continued). "Here we show that breast cancer cells from different subtypes exhibit a variable Orai1:Orai2 expression ratio." (PMID 35008277, 2021). "Consistently, in MDA-MB-231 breast cancer cells knockdown of either STIM1 or Orai1 slows down cell migration, which is due to impairment in the focal adhesion turnover." (PMID 34069353, 2021). "Here, we provide evidence for a different expression of Orai2 and a different relative Orai1:Orai2 expression profile in different breast cancer cell lines." (PMID 35008277, 2021). "Supporting this crucial role, Orai1 overexpression has been described in a variety of breast cancer subtypes, showing a dominant function in triple-negative breast cancer (TNBC) cells." (PMID 34070268, 2021). "SPCA2 has been reported to induce the constitutive activity of Orai1 independently of STIM1 in breast cancer cells." (PMID 34944977, 2021). "Here we provide evidence of the heterogeneous expression of Orai1 and Orai2 between different breast cancer cell lines which leads to the identification of breast cancer cells with high and low Orai1:Orai2 expression ratios." (PMID 35008277, 2021). "A previous study agreed with these conclusions demonstrating that ORAI1 overexpression was significantly correlated with poor prognosis in breast cancer." (PMID 34055617, 2021). "On the one hand, ORAI1 downregulation impairs the migration of breast cancer cells and decreases the invadopodia formation of melanoma cells." (PMID 34831241, 2021). "Knockdown of Orai1 mRNA expression attenuates breast cancer cell migration, and Orai1 overexpression induces migration through increased Ras and Rac levels, using defects in focal adhesion to move the cells." (PMID 33806911, 2021). "In triple-negative MDA-MB-231 breast cancer cells of the MSL subtype, both Orai1 variants as well as AC8 show an enhanced expression at the protein level, but these cells predominantly express AC8, which shifts the Orai1α/AC8 stoichiometry in favor of AC8." (PMID 34070268, 2021). "In breast cancer cells, Orai1 and TRPC6 are upregulated in the estrogen receptor positive (ER+) and triple negative subtypes, and Orai3 is overexpressed exclusively in the ER+ breast cancer subtype." (PMID 34439314, 2021). "We have further analyzed the role of Orai2 on carbachol (CCh)-induced Ca2+ oscillations in SKBR3, BT20 and T47D cells, as representative of breast cancer cells with low and high Orai1:Orai2 expression ratios." (PMID 35008277, 2021). "Silencing NCS‐1 enhanced doxorubicin‐induced breast cancer cell death, which was a phenomenon phenocopied by the silencing of the Ca2+ store refilling channel ORAI1." (PMID 31647602, 2020). "The secretory pathway Ca2+-ATPase (SPCA2), has been elucidated to induce constitutive Ca2+ entry via Orai1 in a breast cancer cell line." (PMID 33333945, 2020). "SICE due to a co-expression of SPCA2 and Orai1 has been reported to drive breast cancer cell growth." (PMID 33333945, 2020). "Especially, in breast cancer cells it is been found that Orai1 interplays with the Ca2+-activated K+ ion channels, SK3, and the voltage-dependent Kv10.1 ion channel." (PMID 33333945, 2020). "Expression of Orai1 was elevated in MDA-MB-231 cells, while the luminal breast cancer cell type MCF7 exhibited high expression of Orai1 and Orai3 and low expression of STIM1 compared with MCF10A." (PMID 32392840, 2020). "Overall, Orai1-mediated SOCE plays a crucial role in breast cancer cell metastasis, while Orai3 is involved in proliferation and cell survival." (PMID 33333945, 2020). "Collectively, these results identify a critical role for NCS‐1 in modulating unstimulated Ca2+ influx likely through ORAI1 channels, since ORAI1 silencing phenocopied the effect of NCS‐1 silencing in GCaMP6m‐MDA‐MB‐231 breast cancer cells." (PMID 31647602, 2020). "A combination of knockdown and rescue strategies in the breast cancer cell line MDA-MB231 has revealed that STIM1 and Orai1 play a major role in breast cancer cell migration." (PMID 33333945, 2020).
breast cancer (continued). "Breast cancer metastasis has been linked to STIM1/Orai1-mediated Ca2+ influx and several studies also highlighted the upregulation of STIM1 and Orai1 in basal breast cancers." (PMID 32764353, 2020). "SOCE was first linked to tumour cell migration and metastasis in MDA-MB-231 breast cancer cells, where siRNA-induced silencing of Orai1 or STIM1, or treatment with the SOCE blocker SKF96365, reduced in vitro migration and invasion." (PMID 32825277, 2020). "Orai1 Ca2+ channels play an important functional role in breast cancer cells supporting a number of cancer hallmarks such as migration, proliferation, or survival." (PMID 31652779, 2019). "The increased expression of Orai1 in the breast cancer cell lines is consistent with the high expression of this protein in cancerous tissue." (PMID 31652779, 2019). "In breast cancer cells, Orai1 was reported to play an important role in migration and the present study provides evidence for a role of AC8 supporting breast cancer cell migration." (PMID 31652779, 2019). "Our analysis of clinical samples from the TCGA database shows that ORAI1 levels are significantly higher in patients with basal breast cancers compared to all other breast cancer molecular subtypes." (PMID 30754719, 2019). "The role of STIM1 and Orai1 in cancer migration and metastasis initially came from studies in breast cancer and cervical cancer." (PMID 31252656, 2019). "Last, in breast cancer cells, σ1R is tightly associated to SK3 (KCNN3) and promotes the functional association of the K+ channel to Orai1 Ca2+ channels." (PMID 31780884, 2019). "The defects in focal adhesion turnover and cell migration in breast cancer cells with STIM1/Orai1 silencing or SOCE blockade were rescued by the small GTPases Ras and Rac." (PMID 31252656, 2019). "The molecular mechanisms by which STIM1/Orai1-dependent SOCE regulates tumor cell migration were highlighted in studies on breast cancer and cervical cancer." (PMID 31252656, 2019). "In this study, we sought to define ORAI3 mRNA expression in breast cancers of different molecular subtypes and compare expression profiles in relation to ORAI1 expression." (PMID 30754719, 2019). "Overexpression of STIM1 and Orai1 is shown in many cancer types like prostate cancer, breast cancer, glioblastoma and hepatocellular carcinoma." (PMID 31366337, 2019). "Attenuating SOCE by knocking down ORAI1 protein expression resulted in the reduction of breast cancer cell proliferation." (PMID 31627357, 2019). "The potential role of increased gene copy number on ORAI3 and ORAI1 expression in breast cancer subtypes was also evaluated." (PMID 30754719, 2019). "Our study demonstrates that elevated ORAI1 is a feature of basal-like breast cancers, while elevated ORAI3 is a feature of luminal breast cancers." (PMID 30754719, 2019). "Kv10.1 has been shown to play an essential role in breast cancer cell proliferation and migration by permitting Ca2+ influx notably via Orai1." (PMID 29872495, 2018). "As SOCE mediated calcium influx regulator Orai1 played a critical role in high salt mediated inflammatory response and paclitaxel resistance, we next tested the impact of Orai1 knock down on the in vivo tumorigenicity of breast cancer cells." (PMID 29861863, 2018). "In the context of SOCE, Orai1 channels have mostly been reported to be overexpressed in a variety of breast cancer cell lines, including the widely studied cell lines ER+ MCF7 and the triple negative MDA-MB-231 breast cancer cells." (PMID 30558192, 2018). "Our results confirm that Orai1 is overexpressed in the breast cancer cell lines and that Orai3 expression is significantly enhanced in MCF7 (p < 0.05; n = 6), as previously reported." (PMID 30223530, 2018). "Previous study demonstrated that Stim1 and/or Orai1 mediated FBS-induced Ca2+ signals in the highly aggressive MDA-MB-231 human breast cancer cell line and in the WM793 human melanoma cell line, thereby promoting tumor cell migration." (PMID 30123430, 2018).
breast cancer (continued). "A functional interaction between Orai1 channels and Kv10.1 channels has also been reported to be involved in collagen-1-promoted breast cancer cell survival." (PMID 30558192, 2018). "We have previously reported that Kv10.1 regulates cell migration in breast cancer cells by regulating basal calcium influx through Orai1." (PMID 29872495, 2018). "Davis and coworkers have reported that STIM1 and Orai1-mediated SOCE is involved in EMT of breast cancer cells, an essential step in cancer metastasis." (PMID 30558192, 2018). "Consistent with this, the expression of a variety of Ca2+ channels is up-regulated in breast cancer cell lines and cancerous tissue, including Orai1, Orai3 and different TRP channels, such as TRPC6, TRPV6 and TRPM8, among others." (PMID 30558192, 2018). "Recently, a functional coupling between Kv10.1 and Orai1 channels has been reported in MDA-MB-231 breast carcinoma cells." (PMID 29872495, 2018). "Although the role of Kv10.1 and Orai1 are extensively studied in proliferation and migration of breast carcinoma cells, little is known about the molecular mechanism(s) underlying their role in cell survival." (PMID 29872495, 2018). "SKF-96365 is an ORAI1 inhibitor that can inhibit breast cancer cell migration in vitro and reduce tumor growth and metastasis in vivo; it also inhibited ORAI1-mediated SOCE and intracellular Ca2+ oscillations in esophageal cancer cells." (PMID 28913175, 2017). "Knockdown of Orai1 in invasive breast cancer cell lines decreased cell migration, whereas its overexpression promoted cellular motility." (PMID 27259269, 2016). "We have recently discovered that a channel complex, formed by SK3 and Orai1, can localize exclusively in to lipid-rafts and controls bone metastasis development in a mouse orthotopic xenografted model of breast cancer." (PMID 27102434, 2016). "As expected, our proposed PSO algorithm has a good performance to identify the protective effects of ORAI1 SNPs against breast cancer in this study." (PMID 26380267, 2015). "The ORAI calcium release-activated calcium modulator 1 (ORAI1) has been proven to be an important gene for breast cancer progression and metastasis." (PMID 26380267, 2015). "The cell- and animal-based studies found that inhibition of ORAI1 gene impeded the migration of breast cancer cells." (PMID 26380267, 2015). "An unconventional interaction between SPCA2, an isoform of the Golgi secretory pathway Ca2+-ATPase, and the Ca2+ influx channel Orai1, has previously been shown to contribute to elevated Ca2+ influx in breast cancer derived cells." (PMID 23840669, 2013). "In breast cancer cells, it was demonstrated that Eag1 (Kv10.1) K+ channel function is required for controlling the Ca2+ entry trough Orai1 channels." (PMID 23970866, 2013). "On the other hand recently the association of Orai1 and K+ channels have been involved in cancer cell migration: SK3 channels functionally associate with the Orai1 channel in a breast cancer MDA-MB-435s within lipid rafts." (PMID 24204345, 2013). "Previously, we had shown that SPCA2 interacts with Orai1 by co-immunoprecipitation from breast cancer derived MCF-7 cells and in HEK293 cells expressing a variety of chimeric and tagged proteins." (PMID 23840669, 2013). "Blocking SOCE, by a pharmacological inhibitor SKF96365 or by siRNA-mediated silencing of STIM1 or Orai1, impaired the focal adhesion turnover and invasive migrations of breast cancer cells." (PMID 23594099, 2013). "In breast cancer cells, it has been demonstrated that Eag1, by regulating membrane potential, controls Ca2+ entry through Orai1 channels." (PMID 23970866, 2013). "This is in contrast to MCF7 breast cancer cells, where ORAI1 silencing almost completely abolishes constitutive ERK1/2 activity." (PMID 22666335, 2012). "Abrogation of Orai1-mediated store-operated calcium channel slows down the turnover of focal adhesion and leads to inhibition of metastasis of breast cancer." (PMID 22778704, 2012).